PENK (proenkephalin)
Diseases named in the same sentence as PENK in open-access papers (continued):
Sharing a sentence is not in itself a finding about the gene and the disease.
Anxiety (4 papers, 2012 to 2021). Intense feelings of nervousness, tension, or panic often arise in response to interpersonal stresses. "We observe significant enrichment of NTSR2, GPR88 and Gabrg1 in chloroquine-activated neurons, and relatively lower expression of OPRM1, PENK and Chrm1, suggesting that these genes could be critical candidates in regulating pruritis and its associated anxiety." (PMID 34032210, 2021). "Furthermore, the loss of neuropeptides, such as NPY, PDYN and PENK, has also been associated with enhanced susceptibility to anxiety-like and depressive-like behavior in mice." (PMID 31251738, 2019). "This would seem contrary to predictions based on animal studies since upregulation of amygdala PENK mRNA expression predicts heightened anxiolytic responses and cannabis subjects exhibited more Neuroticism/anxiety." (PMID 22745721, 2012). "A vast literature has emphasized the role of DRD2 in addiction; but significant evidence also suggests PENK involvement in mood/reward regulation and anxiety that are often correlated with alterations of the mesocorticolimbic system and the striatopallidal circuitry in aversive behavior." (PMID 22745721, 2012).
bone cancer (4 papers, 2011 to 2025). A primary or metastatic malignant neoplasm affecting the bone or articular cartilage. "These investigations were based on preclinical studies that demonstrated the analgesic effects of viral vector-driven proenkephalin expression for the attenuation of neuropathic pain in a model of bone cancer pain." (PMID 22110939, 2011). "HSV-mediated delivery of proenkephalin has been shown to have an analgesic effect in an inflammatory pain model of chronic pain, to be antinociceptive following topical administration in acute pain, to be antiallodynic in neuropathic pain, and to attenuate nociception in a model of bone cancer pain." (PMID 22110939, 2011).
colorectal cancer (4 papers, 2013 to 2022). A primary or metastatic malignant neoplasm that affects the colon or rectum. "In the present study, we propose a panel of tumor-specific methylation genes (NPY, PENK, and WIF1) which in combination show a potential as epigenetic markers for the colorectal cancer diagnosis." (PMID 24289328, 2013).
Huntington disease (4 papers, 2013 to 2025). Huntington disease (HD) is a rare neurodegenerative disorder of the central nervous system characterized by unwanted choreatic movements, behavioral and psychiatric disturbances and dementia. "Using receiver operating characteristic curve analysis, we identified PENK as being the most discriminant CSF protein for stratifying Huntington disease mutation carriers from controls." (PMID 36523269, 2022). "The reduction of pre-enkephalin (pENK) mRNA expression might be an early sign of striatal neuronal dysfunction in Huntington’s disease (HD), due to mutated huntingtin protein." (PMID 24040390, 2013). "Altered levels of CSF PDYN and/or PENK-derived peptides have been reported in Alzheimer’s disease (AD), frontotemporal dementia (FTD), dementia with Lewy bodies (DLB) and Huntington’s disease (HD)." (PMID 35216166, 2022).
Stroke (4 papers, 2014 to 2025). Sudden impairment of blood flow to a part of the brain due to occlusion or rupture of an artery to the brain. "This interpretation is consistent with literature describing kidney–brain vulnerability and hemodynamic contributors to post-stroke AKI, and highlights the need to compare LAR with kidney-specific biomarkers (e.g., proenkephalin) in ICH cohorts." (PMID 41487425, 2025).
Alzheimer disease (3 papers, 2018 to 2022). A progressive, neurodegenerative disease characterized by loss of function and death of nerve cells in several areas of the brain leading to loss of cognitive function such as memory and language. "We previously demonstrated the role of these enzymes in proenkephalin maturation and found some of these neuropeptide fragments in temporal lobe epilepsy and Alzheimer's disease, such as secretogranins for example." (PMID 29122912, 2018).
breast tumor (3 papers, 2014 to 2021). "However, it is worth noting that to our knowledge this is the first time that promoter methylation in CCDC8, HOXD3, PCDH8, PENK, STAT3, SFRP2 and WIFI has been described in primary breast tumours." (PMID 26052355, 2015).
cardiogenic shock (3 papers, 2021 to 2025). "Indeed, patients with cardiogenic shock from the CARDSHOCK trial have been reported to demonstrate high baseline median PENK levels of 105 pmol/L." (PMID 40869560, 2025). "However, data on AKI markers such as plasma proenkephalin (P-PENK) and neutrophil gelatinase-associated lipocalin (P-NGAL) in cardiogenic shock populations are lacking." (PMID 33547528, 2021).
cholestasis (3 papers, 2019 to 2023). Impairment of the bile flow caused by obstruction within the liver, or outside the liver in the bile duct system. "In the present study, we observed that BAM8-22, a cleaved product of proenkephalin, plays important roles in cholestasis-associated pruritus, probably because of CDCA." (PMID 31350433, 2019). "BAM8-22 is one of the by-products of proenkephalin (PENK) that is increased in cholestasis." (PMID 36675074, 2023). "MRGPRX1 could play a role in cholestatic itch as well, both genes for MRGPRC11 (rodent analog of MRGPRX1) and proenkephalin, the precursor of the endogenous MRGPRX1-ligand bovine adrenal medulla peptide 8-22 (BAM8-22), are upregulated in a cholestasis mouse model." (PMID 36385768, 2022).
gastrointestinal stromal tumor (3 papers, 2020 to 2022). "PENK is proposed as a tumor suppressor in gastrointestinal stromal tumors." (PMID 36361532, 2022).
osteosarcoma (3 papers, 2020 to 2022). A usually aggressive malignant bone-forming mesenchymal neoplasm, predominantly affecting adolescents and young adults. "In another study, PENK is found to be downregulated in osteosarcoma (OS)." (PMID 36361532, 2022). "This article reports the effects of proenkephalin (PENK) on osteosarcoma (OS) cell migration." (PMID 32334633, 2020). "Some of these genes are involved in the development of cancer, for instance, PENK is downregulated in osteosarcoma and can activate the PI3K/Akt signaling pathway to restrain osteosarcoma cell migration." (PMID 33737947, 2021).
psoriasis (3 papers, 2021 to 2024). An autoimmune condition characterized by red, well-delineated plaques with silvery scales that are usually on the extensor surfaces and scalp. "This study examined changes in skin mRNA expression of L-kynureninase (Kynu), cathelicidin antimicrobial peptide (Camp), beta-defensin 2 (Defb2), and proenkephalin (Penk) in a mouse model of imiquimod-induced psoriasis." (PMID 39045230, 2024). "In psoriasis lesional skin, PENK mRNA expression was 1.6 times higher (p < 0.01) when compared to psoriasis non-lesional skin." (PMID 34884858, 2021). "The activation of PENK was also achieved by subjecting keratinocytes to inflammatory stimuli and is considered as a part of the epidermal innate immune response, which is itself known to have a role in psoriasis etiology." (PMID 34884858, 2021).
Atrophy (2 papers, 2013 to 2025). Any weakening or degeneration, especially through lack of use. "Baseline NfL, both plasma and CSF, and CSF PENK were predictors of atrophy over time in all brain regions (all FDR < 0.04), even after controlling for the effect of age and CAG (all FDR < 0.12)." (PMID 39825149, 2025). "Consistent with this, we find those participants with the loss of intervening sequence structures exhibit higher rates of caudate and putamen atrophy, and have some of the greatest elevations in CSF NfL and reductions in CSF PENK, which together suggest an acceleration of the degenerative process." (PMID 39825149, 2025).
cannabis dependence (2 papers, 2012 to 2022). Physical and psychological dependence on the drug cannabis. "A strong association was evident between the PENK SNP rs2576573 and cannabis-dependence diagnoses; 61.7% of cannabis-dependent subjects were A/G carriers, compared with 29.2% of controls (p<0.001)." (PMID 22745721, 2012). "Overall, the findings suggest an important role for Neuroticism as an endophenotype linking PENK polymorphisms to cannabis-dependence vulnerability synergistically amplifying the apparent genetic risk." (PMID 22745721, 2012). "Moreover, PENK variants (rs2576573 and rs2609997) significantly related to Neuroticism and cannabis dependence." (PMID 22745721, 2012). "Relative to the reference group, those with both at-risk SNP (PENK rs2576773) and high Neuroticism had an over 8-fold increased clinical diagnosis of cannabis dependence (OR = 8.35, p = .001), compared to those with only Neuroticism (OR = 0.93, p = .99) or the at-risk SNP (OR = 2.41, p = .27)." (PMID 22745721, 2012). "As such, we focused a priori on whether individual genetic differences of the DRD2 and PENK genes associate with cannabis dependence and explored the possible mediation or moderation of intermediate endophenotypes in the genetic associations." (PMID 22745721, 2012). "In evaluating genetic differences between cannabis and control subjects in regard to the DRD2 and PENK genes, it was observed that several DRD2 and PENK SNPs studied modulated cannabis-dependence outcomes." (PMID 22745721, 2012). "Another important finding is the role of PENK SNPs in predicting cannabis dependence." (PMID 22745721, 2012). "Although not specific to cannabis dependence, results from the Greek Caucasian population suggest that the association between the PENK SNPs and Neuroticism could be replicated and generalized to other populations." (PMID 22745721, 2012). "Interestingly, although the cannabis-dependence diagnosis was not assessed in this population, an additive-interaction effect between Neuroticism and both PENK SNPs predicted the history of cannabis use (rs2609997, p = 0.01; rs2576573, p = 0.02)." (PMID 22745721, 2012). "Healthy young adults (18–27 years) with cannabis dependence and without a dependence diagnosis were studied (N = 50/group) in relation to a priori-determined single nucleotide polymorphisms (SNPs) of the DRD2 and PENK genes." (PMID 22745721, 2012).
colon cancer (2 papers, 2013 to 2023). "PENK protein has been shown to act as apoptotic activator particularly under chemotherapy drugs in colon cancer." (PMID 24289328, 2013).
dementia (2 papers, 2011 to 2020). Loss of intellectual abilities interfering with an individual's social and occupational functions. "Enkephalin precursor PENK is a neuropeptide hormone that, together with protachykinin A the precursor of SP, is altered in both dementia and acute neuroinflammatory disorders." (PMID 21726470, 2011). "Recently, highlighted the alteration of the highly correlated PENK and SP in both dementia and acute neuroinflammatory disorders." (PMID 21726470, 2011).
dependence (2 papers, 2012 to 2022). "Short tandem repeats and VNTRs in the cannabinoid receptor 1 (CNR1), glutamate ionotropic receptor NMDA type subunit 2A (GRIN2A), prodynorphin (PDYN), and proenkephalin (PENK) genes were reported to be associated with the vulnerability to schizophrenia and substance dependence." (PMID 35360861, 2022).
Dyskinesia (2 papers, 2017 to 2022). A movement disorder which consists of effects including diminished voluntary movements and the presence of involuntary movements. "The PENK-derived peptides that were affected by dyskinesia in the greatest number of brain regions were PENK and PENK." (PMID 35418178, 2022). "Changes in the striatal expression of proenkephalin and prodynorphin mRNA level have been reported in Parkinsonian rats with L-Dopa-induced dyskinesia." (PMID 29209553, 2017).
hypoglycaemia (2 papers, 2017 to 2024). "While there are very few studies which have investigated the effects of insulin-induced hypoglycaemia on neuropeptides in the adrenal gland, current evidence suggests that recurrent insulin-induced hypoglycaemia increases protein expression of neuropeptides such as NPY, galanin, and proenkephalin." (PMID 38392992, 2024).
kidney damage (2 papers, 2023 to 2026). "Using data from a sub-cohort (440 patients) of the prospective multicentre LifePOC study (1434 patients), proenkephalin A 119-159 (penKid) was assessed for early identification of subclinical kidney damage compared to serum creatinine in emergency patients with a qSOFA score ≥1." (PMID 41706676, 2026).
renal dysfunction (2 papers, 2021 to 2024). "In the present study, the strong association between higher concentrations of PENK and renal dysfunction confirmed previous findings." (PMID 34716603, 2021). "Furthermore, the PENK levels were associated with renal dysfunction on the second day, as measured by the renal component of the Sequential Organ Failure Assessment (SOFA) Score." (PMID 39518330, 2024). "The results from the ALBIOS multicenter randomized trial, involving 956 patients with severe sepsis or septic shock admitted to Italian ICUs, showed that the serum PENK levels were proportional to the severity of renal dysfunction and independently predicted short-term incident AKI." (PMID 39518330, 2024).
small cell carcinoma (2 papers, 2021 to 2024). A neuroendocrine carcinoma composed of small malignant cells which are often said to resemble "oat cells" under the microscope. "PENK can down-regulate scTF and up-regulate B2M in stem-like small cell carcinoma LuCaP 145.1 cells indicative of exit from the stem state and differentiation." (PMID 38595814, 2024). "The neoR LuCaP 145.1 cells showed downregulation of scTF and upregulation of B2M, a response indicative of PENK being able to single-handedly alter the differentiation state of stem-like small cell carcinoma by targeting scTF." (PMID 38595814, 2024). "The identified prostate stromal-specific factor proenkephalin (PENK) was cloned, and transfected into scTF+B2Mlo stem-like small cell carcinoma LuCaP 145.1, reprogrammed luminal-like scTF−B2Mhi LNCaP, and luminal-like scTF−B2Mhi adenocarcinoma LuCaP 70CR." (PMID 34911496, 2021). "To answer whether scTF+B2Mlo small cell carcinoma could respond to stromal factor signaling, we transfected PENK into LuCaP 145.1." (PMID 38595814, 2024). "Our working hypothesis is that PENK could induce differentiation of any stem-like cancer cells such as the small cell carcinoma of many organs." (PMID 38595814, 2024). "Using small cell carcinoma LuCaP 145.1 as a stem-like cell type, we showed that PENK could induce these cancer cells to undergo differentiation with down-regulation of scTF and simultaneously up-regulation of B2M." (PMID 34911496, 2021). "Complementary to this result, PENK could reverse cancer de-differentiation from luminal-like adenocarcinoma to stem-like small cell carcinoma induced by scTF." (PMID 34911496, 2021).
AIDS (1 paper, 2012). A syndrome resulting from the acquired deficiency of cellular immunity caused by the human immunodeficiency virus (HIV). "In that scenario a subject would acquire low DRD2L or PENK expression (and potential synaptic accommodation) prior to acquiring HIV/AIDS." (PMID 22391864, 2012).
anaemia (1 paper, 2019). "In these multivariable models, PENK emerged as a significant marker for death/HF, even following adjustment for clinical variables that have previously been reported as prognostic markers, such as AF and anaemia." (PMID 30767059, 2019).
asthma (1 paper, 2024). "That PA27 has high level of transcripts encoding the antioxidant Gpx3 and proenkephalin (an attenuator of substance P that promotes asthma via the PI3K/Akt/Nfκb pathway in bronchial epithelium) speaks to a potential protective effect mediated by this T cell in lung." (PMID 39141734, 2024).
Brain atrophy (1 paper, 2025). Partial or complete wasting (loss) of brain tissue that was once present. "We demonstrate the accumulation of somatic expansion of the HTT CAG repeat in blood DNA over time in HD-ISS stages 0 and 1 and, critically, show that it is associated with both brain atrophy and CSF NfL, a marker of neuronal–axonal injury, and CSF PENK, a surrogate marker of striatal MSN state." (PMID 39825149, 2025). "The presence of neuronal damage within HD-ISS stage 0 is further supported by the evidence of substantially elevated rates of brain atrophy and a corresponding reduction in CSF PENK levels." (PMID 39825149, 2025). "For example, we demonstrate that baseline NfL and PENK levels predict subsequent brain atrophy, and the potential to establish cutoffs for enriching HD-ISS stage 0 based on these biofluids holds significant promise." (PMID 39825149, 2025). "We identify brain atrophy, elevated levels of CSF NfL, a marker of neuronal damage, and reduced levels of CSF PENK, a marker of striatal MSN state, in the earliest adult HD cohort studied to date." (PMID 39825149, 2025).
Cerebral ischemia (1 paper, 2007). Restriction of arterial blood supply to the brain associated with insufficient oxygenation to support the metabolic requirements of the tissue. "Proenkephalin has been characterized as an immediate-early gene in the hippocampus in various seizure models, we did however not find data concerning effects of proenkephalin on neuronal survival or possible functions in cerebral ischemia." (PMID 17937787, 2007).
chronic heart failure (1 paper, 2019). "Proenkephalin (PENK), a stable endogenous opioid biomarker related to renal function, has prognostic utility in acute and chronic heart failure." (PMID 30767059, 2019).
Crohn disease (1 paper, 2023). A gastrointestinal disorder characterized by chronic inflammation involving all layers of the intestinal wall, noncaseating granulomas affecting the intestinal wall and regional lymph nodes, and transmural fibrosis. "This study is the first study to comprehensively assess changes in the concentrations of β-endorphin, proenkephalin, and big dynorphin, over the course of Crohn’s disease." (PMID 37509676, 2023).
epilepsy (1 paper, 2025). A brain disorder characterized by episodes of abnormally increased neuronal discharge resulting in transient episodes of sensory or motor neurological dysfunction, or psychic dysfunction. "Taken together, our results suggest that a few neuronal subtypes, particularly the PVALB_RGS5, VIP_CRH, and SST_PENK subtypes, are closely associated with pediatric epilepsy." (PMID 40313715, 2025). "Among the inhibitory neurons, the number of interaction pairs tended to be greater in the epilepsy group than the control group, particularly for the PVALB_RGS5, VIP_CRH, and SST_PENK subtypes, and the VIP_CRH subtype showed the most significant increase." (PMID 40313715, 2025). "Among the identified neuronal subtypes, the three inhibitory neuronal subtypes PVALB_RGS5, VIP_CRH, and SST_PENK presented prominent transcriptomic alterations related to epilepsy." (PMID 40313715, 2025).
glaucoma (1 paper, 2021). Increased pressure in the eyeball due to obstruction of the outflow of aqueous humor. "PENK (cluster P) which is localized to the GLC1D glaucoma locus was downregulated in both cell lines at comparable levels (CAβ3 FC = −4.23; WTβ3 FC = −4.96)." (PMID 34440692, 2021).